G6PD (glucose-6-phosphate dehydrogenase)
Diseases named in the same sentence as G6PD in open-access papers (continued):
Sharing a sentence is not in itself a finding about the gene and the disease.
melanoma (continued). "G6PD mutant melanomas exhibited increased levels of reactive oxygen species, decreased NADPH levels, and depleted glutathione as compared to control melanomas." (PMID 35110412, 2022). "The fractional enrichment of (m+3) lactate was also significantly higher in the G6PD mutant as compared to control melanoma cells." (PMID 35110412, 2022). "Malic enzyme activity, based on the ratio of pyruvate (m+3) to malate (m+4), was significantly higher in the G6PD mutant as compared to control melanoma cells." (PMID 35110412, 2022). "To test if antioxidants would rescue the effect of glutaminase inhibition on the growth of G6PD mutant and control melanomas, we treated A375 cells with a low concentration of CB-839 (1 nM)." (PMID 35110412, 2022). "This generated a new metabolic vulnerability as G6PD mutant melanomas were more dependent upon glutaminase than control melanomas, both for oxidative stress management and anaplerosis." (PMID 35110412, 2022). "ME1, which localizes to the cytoplasm, was expressed by most melanomas but it tended to higher in G6PD mutant as compared to control melanomas." (PMID 35110412, 2022). "To test if G6PD mutant melanomas exhibit higher GDH activity, we cultured cells with 15N-glutamine (labeled in the α-position) and measured the production of 15NH4+ by gas chromatography/mass spectrometry (GC/MS)." (PMID 35110412, 2022). "G6PD mutant melanoma cells were therefore far more sensitive to glutaminase inhibition than control melanoma cells." (PMID 35110412, 2022). "The data thus suggest that melanoma cells experienced higher levels of oxidative stress when G6PD function was decreased." (PMID 35110412, 2022). "Infusion of [U-13C] glutamine enriched the circulating glutamine, lactate, and pyruvate pools in the blood to a similar extent in mice transplanted with G6PD mutant and control melanomas." (PMID 35110412, 2022). "Melanoma cell lines have been demonstrated to have elevated expressions and activities of G6PD compared with normal melanocytes, and the knockdown of G6PD in xenograft models show G6PD facilitates melanoma growth in vivo." (PMID 35326683, 2022). "G6PD mutant melanomas had significantly decreased G6PD enzymatic activity and depletion of intermediates in the oxidative pentose phosphate pathway." (PMID 35110412, 2022). "Consistent with the results in culture, the fractional enrichment of glutamine (m+5) in tumors was significantly higher in the G6PD mutant as compared to control melanomas." (PMID 35110412, 2022). "CB-839 treatment significantly reduced the levels of at least some TCA cycle intermediates in all three melanomas, particularly in G6PD mutant melanomas." (PMID 35110412, 2022). "G6PD or PGD deficiency (23, –25) reduce the growth of some cancers, including melanoma, but G6PD deficiency has little effect on primary tumor formation by K-Ras–driven epithelial cancers." (PMID 35110412, 2022). "Glutaminase inhibition typically reduced GSH/GSSG ratios to a greater extent in the G6PD mutant as compared to control melanoma cells." (PMID 35110412, 2022). "Both GSH and Trolox partially rescued the much more profound effects of glutaminase inhibitor on the growth of G6PD mutant melanoma cells." (PMID 35110412, 2022). "To assess this in vivo, we infused [U-13C] glutamine into mice xenografted with G6PD mutant or control M481 melanomas." (PMID 35110412, 2022). "G6PD mutant melanomas compensated by increasing malic enzyme activity and glutamine consumption, both to increase oxidative stress resistance and to replenish tricarboxylic acid (TCA) cycle intermediates through anaplerosis." (PMID 35110412, 2022). "We first compared the consumption of glutamine by G6PD mutant and control melanoma cells in culture." (PMID 35110412, 2022). "Oxidative stress thus appears to have contributed to the effects of glutaminase inhibition on the growth of G6PD mutant and control melanoma cells." (PMID 35110412, 2022).
melanoma (continued). "Expressions of GPX2, GPX4, GSR, and G6PD have been found to be elevated in melanomas and other cancers." (PMID 35326683, 2022). "Metastatic disease burden and the percentage of mice that spontaneously formed macrometastases was always significantly lower in mice with the G6PD mutant as compared to control melanomas." (PMID 35110412, 2022). "To further explore this, we tested if glutaminase inhibition depleted TCA cycle intermediates to a greater extent in the G6PD mutant as compared to control melanomas." (PMID 35110412, 2022). "This ratio was consistently and significantly higher in G6PD mutant as compared to control melanoma cells." (PMID 35110412, 2022). "We assessed the contribution of glutamine (m+5) to TCA cycle intermediates in G6PD mutant and control melanomas growing subcutaneously." (PMID 35110412, 2022). "The increased glutaminolysis in G6PD mutant melanomas decreased oxidative stress and replenished TCA cycle intermediates." (PMID 35110412, 2022). "Taken together, the data suggest that reduced G6PD function renders melanoma cells more dependent upon glutaminolysis." (PMID 35110412, 2022). "To address this, we mutated the substrate binding site of glucose 6-phosphate dehydrogenase (G6PD), which catalyzes the first step of the pentose phosphate pathway, in patient-derived melanomas." (PMID 35110412, 2022). "To test if these cells are more dependent upon the pentose phosphate pathway during metastasis, we generated three G6PD mutant melanomas, including two patient-derived xenografts and one human melanoma cell line." (PMID 35110412, 2022). "The role of G6PD in cooperation with NADPH oxidase 4 (NOX4) for the support of redox homeostasis has been related to melanoma cells in vitro, indeed targeting both enzymes suppressed cell proliferation." (PMID 33091721, 2020). "Taken together, G6PD status is linked to cell proliferation and cellular malignancy, possibly through the STAT3/5 ratio, in mice melanoma cells." (PMID 31500396, 2019). "Using a melanoma cell line xenograft nude mouse model, mice injected with wild-type G6PD cells display faster tumor formation and larger tumor size than those mice with G6PD-deficient cells." (PMID 31500396, 2019). "G6PD status in melanoma cells is positively correlated with the expression of the cell cycle proteins, including cyclin D1 and cyclin E." (PMID 31500396, 2019). "Consistent with previous reports that associated the Nrf2 pathway with SFN-induced chemoprevention, we found that the Nrf2 target genes HMOX1, TXNRD1, GCLC, GCLM, AKR1B10 and G6PD were upregulated after melanoma treatment." (PMID 28864908, 2018). "The current study further explores the relationship and mechanism of action of G6PD and melanoma cell proliferation and apoptosis using a mouse model of tumor formation." (PMID 23693134, 2013). "G6PD was previously shown to be highly expressed in human melanoma cells, exhibiting a close relationship to the growth and proliferative phenotype of tumor cells, although no in vivo study has confirmed this finding." (PMID 23693134, 2013). "In the current study, as expected, expression and activity of G6PD showed a positive correlation with melanoma weight, growth, and differentiation." (PMID 23693134, 2013).
melanoma (continued). "G6PD is involved in the growth, proliferation, and apoptosis of neoplastic tumors in nude mice models of melanoma." (PMID 23693134, 2013). "Loss of glucose-6-phosphate dehydrogenase (G6PD), a key enzyme in the pentose phosphate pathway, reduced melanoma metastasis without obvious impact on the formation of primary subcutaneous tumors." (PMID 40617808, 2025). "Indeed, it has been observed that loss of the glucose 6-phosphate dehydrogenase (G6PD) function, a key enzyme in PPP, increases oxidative stress and glutaminolysis in metastatic melanoma cells." (PMID 40573249, 2025). "For instance, melanoma cells are dependent on G6PD to manage oxidative stress during metastasis, albeit a compensatory metabolic reprogramming aiding ROS protection might arise as a consequence of G6PD deficiency." (PMID 38115544, 2024). "Targeted therapy, when combined with G6PD inhibitors, may help overcome resistance in malignant melanoma." (PMID 39796677, 2024). "The application of these agents in clinical trials for the treatment of advanced melanoma may provide valuable insights into the efficacy and potential benefits of G6PD inhibitors." (PMID 39796677, 2024). "Thus, G6PD plays an extremely important role in the management of melanoma cells, participating in many cascades of biochemical reactions including anti-apoptosis and fast growth, which enable their aggressive nature." (PMID 37185731, 2023). "To test whether melanoma metastasis depended on the oxidative pentose phosphate pathway, we used CRISPR to make small deletions in exon 6 of G6PD in three melanomas including the A375 human melanoma cell line and two patient-derived melanomas (M481 and M214)." (PMID 35110412, 2022). "To test whether this contributed to the dependence of G6PD mutant melanomas upon glutaminolysis, we compared the abundance of TCA cycle intermediates between G6PD mutant and control melanomas growing subcutaneously." (PMID 35110412, 2022). "This suggests that G6PD mutant melanomas increase both GDH and malic enzyme activity." (PMID 35110412, 2022). "The role of G6PD in cancer redox biology, including for melanomas, has recently been reviewed." (PMID 35326683, 2022). "Reduced G6PD function had little effect on the formation of primary subcutaneous tumors, but when these tumors spontaneously metastasized, the frequency of circulating melanoma cells in the blood and metastatic disease burden were significantly reduced." (PMID 35110412, 2022). "Thus, both isotope tracing and metabolomics data suggest that G6PD mutant melanomas have diminished flux through the oxidative pentose phosphate pathway." (PMID 35110412, 2022). "GDH activity was significantly increased in the G6PD mutant as compared to control melanomas." (PMID 35110412, 2022). "The ratios of GSH to GSSG were significantly lower in G6PD mutant as compared to control melanomas." (PMID 35110412, 2022). "However, the magnitude of the rescue in G6PD mutant cells was small, raising the possibility that glutamine consumption promoted the growth of G6PD mutant melanoma cells through additional mechanisms beyond its role in suppressing oxidative stress." (PMID 35110412, 2022). "A human A375 cell line melanoma xenograft murine model has shown that deletion of glucose-6-phosphate dehydrogenase (G6PD), which catalyzes the pentose-phosphate pathway, upregulates the antiapoptosis proteins Bcl-2 and Bcl-xL, whereas the tumor suppressor, Fas, was shown to be downregulated." (PMID 34067095, 2021). "Indeed, the inhibition of G6PD sensitized malignant melanoma cells A375 to oxidative stress, decreased proliferation and induced apoptosis." (PMID 33091721, 2020). "Knockdown of G6PD in melanoma cell lines leads to the reduction of phosphorylated STAT5." (PMID 31500396, 2019). "Overexpression of G6PD in human melanoma cells enhances phosphorylated STAT5." (PMID 31500396, 2019). "Another important finding from ET in the melanoma analyses is the identification of G6PD." (PMID 27042214, 2016).
melanoma (continued). "Because of the broad affects of G6PD, it may provide an excellent target for the development of improved treatment methods and prognostic indicators for melanoma patients." (PMID 23693134, 2013). "Thus, inhibition of G6PD expression with antisense oligonucleotides is an effective tool for the treatment of melanoma, but it should be noted that this method is most suitable for local treatment, since central administration leads to a large number of side effects." (PMID 37185731, 2023). "The regulation mechanism of G6PD and pathological change in human melanoma growth remains unknown." (PMID 23693134, 2013). "Similarly, high expression was observed in the A375-WT group, suggesting that G6PD may regulate cell apoptosis of melanoma through apoptosis-related factors Fas, Bcl-2, and Bcl-xL." (PMID 23693134, 2013). "G6PD regenerates NADPH and silencing of G6PD and NADPH oxidase 4 (NOX4) resulted in G1/S cell cycle arrest and inhibited melanoma cell activity." (PMID 38194707, 2024). "In melanoma, highly activated STAT3 and STAT5, along with a potential role of G6PD in cancer mediated by these STAT proteins, has been observed." (PMID 39796677, 2024). "We previously demonstrated that G6PD, the key enzyme of the PPP, is upregulated, and its enzyme activity is increased in melanoma, which can promote the proliferation of melanoma cells and inhibit apoptosis." (PMID 36203561, 2022). "To test if glutaminase inhibition increased oxidative stress in G6PD mutant melanoma cells, we measured ROS levels (CellRox green) and GSH to GSSG ratios in G6PD mutant and control melanoma cells treated in culture with 100 nM CB-839 or vehicle control." (PMID 35110412, 2022). "When pentose phosphate pathway function was impaired by reduced glucose 6-phosphate dehydrogenase (G6PD) function, melanoma cells increased malic enzyme activity and glutamine consumption." (PMID 35110412, 2022). "The antioxidant role of glucose-6-phosphate dehydrogenase (G6PD), the rate-limiting enzyme of PPP that catalyzed the first reaction with the production of NADPH, has been studied in an in vitro melanoma model." (PMID 33091721, 2020). "Another study showed that high expression of G6PD promotes melanoma growth via the signal transducer and activator of transcription 3/5 (STAT3/5) pathway in a human melanoma xenograft model." (PMID 33091721, 2020). "The close relationship between G6PD and NOX4 maintains ROS homeostasis and promotes downstream redox signaling, including STAT3, c-SRC and SHP2, in melanoma cells." (PMID 31500396, 2019). "In addition, the expression of G6PD and its activity, cell cycle-related proteins, apoptosis-related proteins, and STAT3/STAT5 in tumor tissues were determined in order to provide full documentation of the regulatory mechanisms involved with in vivo melanoma growth associated with G6PD." (PMID 23693134, 2013). "Additionally, intermediates from the pentose phosphate pathway, such as glucose 6-phosphate dehydrogenase (G6PD) and 6-phosphogluconate dehydrogenase (PGD), are found to be more abundant in metastases compared to subcutaneous primary melanomas." (PMID 40725201, 2025). "The absence of G6PD in mouse melanoma cells enhances apoptosis by increasing the FAS level and decreasing the Bcl-2 and Bcl-xL levels." (PMID 37185731, 2023). "ROS levels were usually higher in the G6PD mutant as compared to control melanoma cells (including A375 and M481, but not M214)." (PMID 35110412, 2022). "The G6PD mutant melanomas consistently had lower NADPH/NADP+ ratios as compared to control cells, primarily due to a decrease in NADPH levels in the G6PD mutant melanomas." (PMID 35110412, 2022). "We asked whether low expression of the direct NRF2 targets G6PD and SOD1 would influence melanoma adhesion and invasion." (PMID 34951143, 2022). "Lack of G6PD in mice melanoma cells enhances apoptosis by upregulating Fas and downregulating Bcl-2 and Bcl-xL." (PMID 31500396, 2019).
melanoma (continued). "Additionally, we also found up-regulation of two metabolic biosynthesis key players, G6PD and ATP6AP1, in TFAM down samples, suggesting that TFAM levels influence the expression of genes coding for key components of metabolic pathways in melanoma." (PMID 30242167, 2018). "G6PD may be regulated apoptosis and expression of cell cycle–related proteins through phosphorylation of transcription factors STAT3 and STAT5, thus mediating formation and growth of human melanoma cells." (PMID 33630390, 2021). "G6PD may regulate apoptosis and expression of cell cycle-related proteins through phosphorylation of transcription factors STAT3 and STAT5, thus mediating formation and growth of human melanoma cells." (PMID 23693134, 2013). "In A375 tumors, G6PD mutant cells had significantly lower levels of glutamate, succinate, fumarate, malate, and citrate; however, in M214 and M481 melanomas, G6PD mutant tumors did not have lower levels of any TCA cycle intermediate as compared to control cells." (PMID 35110412, 2022). "This is further supported by the finding that in melanoma cells (which also have high PPP activity), when G6PD function was impaired, there was no reduction in erythrose-4-phosphate levels." (PMID 36276829, 2022).